GIP (gastric inhibitory polypeptide)
Diseases named in the same sentence as GIP in open-access papers (continued):
Sharing a sentence is not in itself a finding about the gene and the disease.
Obesity (continued). "Specifically, subjects with AUD who had a prescription for GIP/GLP-1 RA had an incident alcohol intoxication rate that was 49%, 42%, and 42% lower, respectively, when stratified by type 2 diabetes, obesity, and type 2 diabetes and obesity." (PMID 40722294, 2025). "Multi-agonist therapies targeting combinations of gut hormone receptors—such as GLP-1, glucose-dependent insulinotropic polypeptide (GIP), and glucagon receptors—represent a novel approach to enhancing metabolic outcomes in obesity treatment." (PMID 40731921, 2025). "GIP promotes de novo lipogenesis in white adipocytes and induces fat/lipid storage in adipocytes with GIP knockouts in adipocytes reducing HDF-induced obesity." (PMID 40696355, 2025). "Non-pharmacological approaches, such as diet and exercise, are first-line management strategies for obesity, but novel drugs like glucagon-like peptide (GLP-1) and gastric inhibitory polypeptide (GIP) receptor agonists show promising results for weight loss." (PMID 41431533, 2025). "This review outlines the anti-obesity effects and mechanisms of action of emerging anti-obesity drugs, including GLP-1 receptor agonists and dual GIP/GLP-1 receptor agonists." (PMID 40607142, 2025). "Two phase 3 trials have addressed the potential positive effect of the dual GIP and GLP-1 receptor agonist (tirzepatide) for obesity (SURMOUNT-1, patients with obesity only, and SURMOUNT-2, for patients with obesity and type 2 diabetes)." (PMID 39881371, 2025). "Incretin-based therapies represent a novel treatment for both T2DM and obesity, relying on the insulinotropic actions of the gut hormone GLP-1 and, most recently, on the combined action of GLP-1 and the GIP hormones." (PMID 40566497, 2025). "Pharmacological modulation of glucagon-like peptide-1 (GLP-1) and glucose-dependent insulinotropic polypeptide (GIP) through dual GIP/GLP-1 receptor agonists, commonly used for diabetes and obesity, shows promise in reducing alcohol consumption." (PMID 40931165, 2025). "Therapeutic options such as GLP-1 receptor agonists, dual GIP/GLP-1 receptor agonists, SGLT2 inhibitors, and orlistat have significantly expanded the available treatments for obesity and Type 2 Diabetes." (PMID 40565464, 2025). "The dual agonists of GIP/GLP-1 maridebart cafraglutide (AMG 133) and survodutide (BI 456906) are investigational drugs with robust anti-obesity efficacy." (PMID 39407846, 2024). "The biomarkers GLP-1, GIP, MCP-1, and IGFBP7 hold promise in improving diagnostics for diabetes and obesity." (PMID 38255264, 2024). "If the ultimate goal is to translate sVNS to the clinic to treat obesity, then the technology must compete with well-established bariatric surgical treatments as well as the newer semaglutide GLP-1 and tirzepatide GLP-1/GIP agonists." (PMID 38040984, 2024). "In prior studies, FABP5 was highly and exclusively expressed in enteroendocrine K cells, maintaining the normal level of glucose-dependent insulinotropic polypeptide (GIP), which regulates diet-induced obesity in response to fat ingestion." (PMID 39542983, 2024). "The identification and exploration of biomarkers such as GLP-1, GIP, MCP-1, and IGFBP-7 have provided valuable insights into the complex pathophysiology of metabolic disorders, including type 2 diabetes and obesity." (PMID 38255264, 2024). "Tirzepatide is a novel once-a-week dual glucose-dependent insulinotropic polypeptide (GIP) and glucagon-like peptide-1 (GLP-1) receptor agonist, recently approved for type 2 diabetes mellitus (T2DM) and obesity." (PMID 38665722, 2024). "Biomarkers identified as potential factors associated with the development of metabolic disorders such as type 2 diabetes and obesity, namely GLP-1, GIP, MCP-1, and IGFBP-7, have been the subject of extensive scientific research." (PMID 38255264, 2024).
Obesity (continued). "Tirzepatide is a once-weekly subcutaneous injection of glucose-dependent insulinotropic polypeptide (GIP) and glucagon-like peptide-1 (GLP-1) receptor agonist approved in the US and EU for the treatment of T2D and obesity." (PMID 38341541, 2024). "Incretin-based therapies (GLP-1 receptor agonists, and dual GIP/GLP-1 receptor agonists) are used clinically to treat diabetes and obesity." (PMID 39770498, 2024). "Because GIP effectiveness on GSIS is lost in T2D patients, its potential as anti-diabetic/anti-obesity drug has been neglected for a while." (PMID 39549913, 2024). "In this dataset of 205 participants spanning a wide BMI range, fasting GIP, insulin and PYY were shown to be important classifiers between participants with healthy BMI, overweight and obesity." (PMID 38490484, 2024). "There is an impressive number of obesity management medications under investigation, such as GLP1/glucagon dual agonists, GIP/GLP1 dual agonists, GIP/GLP1/glucagon tri-agonists, leptin sensitizers, etc.." (PMID 39274320, 2024). "Apart from that, gastrointestinal hormones like ghrelin and glucose-dependent insulinotropic polypeptide (GIP), involved in regulation of energy homeostasis, insulin secretion, and appetide control, have been shown to be dysregulated in obesity." (PMID 37266430, 2023). "This study shows that microbiome changes induced by bariatric surgery prevent diet-induced obesity and NAFLD by altering GIP signaling." (PMID 36732495, 2023). "For this, we conducted an in vitro study in which the VAT of individuals with obesity with different glycemic statuses and normal-weight euglycemic control was exposed to GLP-1, GIP and glucagon in different concentrations." (PMID 37233628, 2023). "In sum, these data suggest that, in individuals with obesity and insulin resistance, GLP-1, GIP and glucagon are likely to increase AT’s metabolic efficiency despite this effect being attained via different mechanisms and potentially acting in synergy." (PMID 37233628, 2023). "In the future, GIP, GLP-1, and glucagon tri-agonists are promising for patients with T2D and/or obesity." (PMID 37701904, 2023). "This drug, based on the GIP sequence and attached to a C20 diacid moiety, was developed by Eli Lilly and approved by the FDA and EMA in 2022 for the treatment of adults with obesity or overweight with weight-related comorbidities." (PMID 37049856, 2023). "The subsequent advance in anti-obesity treatment was the development of dual incretins, such as tirzepatide, a dual GLP-1 and glucose-dependent insulinotropic polypeptide (GIP) agonist, and cotadutide, a dual GLP-1 and glucagon agonist." (PMID 38146424, 2023). "Unimolecular co-agonists at the receptors for GIP and the glucagon-like peptide-1 (GLP-1) are among the most promising drugs in clinical development for the treatment of obesity and diabetes." (PMID 37592302, 2023). "In adults with T2D and obesity, GLP-1 RA or GIP/GLP-1 receptor co-agonists SHOULD BE CONSIDERED for improving weight loss." (PMID 37468901, 2023). "Building on that concept, the combined GIP and GLP-1 RAs have been proposed as a novel therapeutic option for T2DM and obesity." (PMID 37141329, 2023). "On the basis of these findings, dual-receptor agonists for GLP-1/GIP, GLP-1/glucagon as well as triple-receptor agonists were propagated and successively developed for the treatment of T2D and obesity." (PMID 36313764, 2022). "Their results suggested that FXa-PAR2 signaling in the intestinal epithelium is an important factor in the regulation of postprandial glucose-dependent insulinotropic polypeptide (GIP) and early onset obesity." (PMID 36079779, 2022). "The scientific interest in the management of not only T2DM but also obesity via the use of GLP-1 receptor agonist and the older one, glucose-dependent insulinotropic polypeptide (GIP), led to the development of newer agents." (PMID 36362984, 2022).
Obesity (continued). "These three molecules, GLP-1, GIP and GCG, are currently taking center stage in promising drug development strategies focusing on obesity and diabetes." (PMID 36552107, 2022). "Tirzepatide is a novel, once weekly, dual GIP/GLP-1 receptor agonist and is under development for the treatment of type 2 diabetes (T2D) and obesity." (PMID 35210595, 2022). "The most important factors related to obesity, namely, HDL, LDL, total cholesterol, total glycerides, insulin, glucose, and gastric inhibitory peptides (GIP) levels, were analyzed in this study." (PMID 35204193, 2022). "Ablation of GIP in Lepob/ob mice, did not prevent body weight gain and insulin resistance, suggesting that endogenous GIP may not have a role in the development of obesity in leptin deficient mice, indicating that the crosstalk between leptin and GIP secretion warrants further investigation." (PMID 35409202, 2022). "Multiple dual receptor agonists are in clinical development for the treatment of obesity, including GLP‐1/GIP and GLP‐1/glucagon receptor agonists." (PMID 34713962, 2022). "GIPR agonism alone has been shown to reduce bodyweight in mice with obesity, as observed with GIPR agonists with a longer half‐life than endogenous GIP." (PMID 34713962, 2022). "Tirzepatide is a novel, once-weekly, injectable, dual glucose-dependent insulinotropic polypeptide (GIP) and GLP-1 RA, is being developed for the treatment of type 2 diabetes (T2D) and obesity with CV safety demonstrated in the late phase clinical program." (PMID 36002856, 2022). "Dual GIP/GLP-1 agonists are in development as potential new anti-diabetic and anti-obesity treatments." (PMID 33803183, 2021). "In this review, we describe the physiology of two known incretins—glucose-dependent insulinotropic polypeptide (GIP) and glucagon-like peptide-1 (GLP-1), and their role in obesity and related cardiometabolic disorders." (PMID 33503878, 2021). "The glucose-dependent insulinotropic polypeptide (GIP) and the glucagon-like peptide-1 (GLP-1) receptor are important targets in the treatment of both type 2 diabetes mellitus (T2DM) and obesity." (PMID 32903502, 2020). "In other words, both GIP agonism (normally thought to be inactive) and GIP antagonism appear to be effective in T2DM and obesity." (PMID 32459834, 2020). "Tirzepatide (LY3298176) is a dual GIP and GLP-1 receptor agonist under development for the treatment of type 2 diabetes mellitus (T2DM), obesity, and nonalcoholic steatohepatitis." (PMID 32730231, 2020). "As previously discussed, the beneficial effect of GIP receptor activation is difficult to understand, as the effect of GIP is impaired in patients suffering from T2DM and obesity." (PMID 32459834, 2020). "GIP also increases IL-6 expression and production in adipocytes in the presence of TNF-α, which is induced by obesity and enhances HFD-induced insulin resistance through IL-6 signaling." (PMID 31977316, 2020). "A connection between obesity and GIP has been reported: Plasma GIP levels in obese humans are increased, and GIPR knockout mice are resistant to high-fat diet (HFD)-induced obesity." (PMID 31509948, 2019). "Although DIO mice are a useful model for studying the direct effect of HFD on GIP secretion, HFD feeding induces obesity." (PMID 31509948, 2019). "Between the two incretin hormones GIP and GLP-1, GIP is involved in lipid metabolism, and elevated plasma GIP level promotes hyperinsulinemia and obesity-induced IR development." (PMID 30862092, 2019). "The treatment of obesity and type 2 diabetes with metabolic surgery influences the physiological role of incretins like GLP-1, GIP, and PYY, which are important players in glucose homeostasis improvement." (PMID 28840471, 2018). "Although the effect of GIP on human appetite and food intake, if any, is not clear, there is limited animal evidence to suggest it may act to stimulate food intake; GIP receptor-deficient mice are resistant to diet-induced obesity." (PMID 29267221, 2017).
Obesity (continued). "Importance of this research is clearly evident as a novel monomeric peptide triagonist acting on GLP-1, GIP, and GCG receptors has been found to be the most effective among existing pharmacological agonists/strategies in reversing obesity in mice." (PMID 28223965, 2017). "We observed that GIP mRNA was elevated dramatically by HFD in the small intestine of DIO mice, which correlates to elevated serum GIP in obesity." (PMID 26266950, 2015). "Taken together, these results suggest that the lower response of GIP and GLP-1 at week 1 likely occurred due to obesity." (PMID 23762590, 2012). "However, the question as to whether long-term elevation of GIP production causes detrimental pro-obesity effects has not been directly addressed and we have therefore examined responses of transgenic overexpression of GIP (GIP Tg) mice to HF diet feeding." (PMID 22802954, 2012). "Whilst the enteroendocrine cells producing GIP and GLP-1 are therefore attractive targets for the treatment of diabetes and obesity, our understanding of their physiology is fairly limited." (PMID 20204054, 2010). "This work highlights the suitability of using postprandial plasma GIP as a biomarker for metabolic disturbances of increased adiposity, even in the absence of obesity." (PMID 41528263, 2026). "The 2025 ACC scientific statement on obesity in heart failure addresses the therapeutic role of GLP‐1 and dual GIP/GLP‐1 agonists for patients with HFpEF and obesity, and it recommends multidisciplinary care pathways to integrate anti‐obesity medications safely and effectively." (PMID 41566974, 2026). "This work highlights the suitability of postprandial plasma GIP as a biomarker of metabolic disturbances of increased adiposity, even in the absence of obesity." (PMID 41528263, 2026). "In recent years, glucagon-like peptide-1 receptor agonists (GLP-1 RAs, e.g., semaglutide) and hybrid gastric inhibitory polypeptide (GIP) analogs and GLP-1 RAs (GIP/GLP-1 RAs, e.g., tirzepatide) have emerged as novel pharmacological agents for the treatment of obesity." (PMID 40507553, 2025). "This strategy effectively reduced obesity and improved glucose and glucose tolerance, accompanied by favorable changes in serum metabolic parameters, which were less pronounced with single PTT or GIP alone NPs." (PMID 41256211, 2025). "Considering recent findings, it is further worth exploring whether GLP-1 or dual GIP/GLP-1 receptor agonists could prevent dementia in stroke patients with prediabetes and obesity by preventing the progression to diabetes." (PMID 40893447, 2025). "Modern therapies used in the treatment of obesity, such as dual Glucagon-like peptide-1/GLP-1 and Gastric inhibitory polypeptide/GIP analogs (tirzepatide), have been shown to reduce the severity of obstructive sleep apnea symptoms, thereby indirectly improving respiratory function in these patients." (PMID 40863398, 2025). "The physiologic role of GIP to regulate prandial glucose and lipid metabolism coupled with numerous preclinical studies commend GIPR antagonism as the appropriate mechanism to treat obesity." (PMID 40507574, 2025). "Therefore, the insulinotropic, glucoregulatory and anorectic actions of GIP and GLP-1 have supported the development of incretin-based therapies for the treatment of T2D and obesity." (PMID 40004833, 2025). "GIP also suppresses adipose tissue inflammation, as assessed through reduced cytokine expression and decreased adipose tissue infiltration of IFN-γ-producing CD8(+) and CD4(+) T cells in mice with diet-induced obesity." (PMID 40024571, 2025). "Notably, however, kisspeptin-10 intervention augmented the overall number of GIP and GLP-1 ileal positive cells, with both hormones recently attracting attention in respect to benefits for obesity, diabetes and various other metabolic conditions." (PMID 41301510, 2025). "Hence, restoring GIP signaling by TRZ can reduce body weight and improve the insulin sensitivity in obesity." (PMID 40498212, 2025).
Obesity (continued). "In this review, we explore the multifaceted nature of the obesity paradox in HF, with a focus on emerging anti-obesity incretin-mimetic therapies, such as glucagon-like peptide-1 receptor agonists (GLP-1 RAs) and dual GLP-1/glucose-dependent insulinotropic polypeptide (GIP) receptor agonists." (PMID 41400711, 2025). "Tirzepatide is a once‐weekly, dual glucose‐dependent insulinotropic polypeptide (GIP) and GLP‐1 receptor agonist that has demonstrated dose‐dependent efficacy in people with obesity, T2D or both, in terms of glycaemic control and bodyweight reduction in clinical trials." (PMID 40555920, 2025). "More recently, dual and triple incretin agonists, targeting combinations of GLP-1, glucose-dependent insulinotropic polypeptide (GIP), and glucagon (GCG), have achieved even greater weight reductions in clinical trials, raising the prospect of unprecedented efficacy in medical obesity treatment." (PMID 41465555, 2025). "Recently, there has been an intensive increase in the use of novel drugs in the treatment of obesity, such a liraglutide (glucagon-like peptide-1 (GLP-1) agonist) and tirzepatide (a glucose-dependent insulinotropic polypeptide (GIP) and GLP-1 receptors agonist)." (PMID 39941741, 2025). "The third generation of nutrient-stimulated hormone-based (NuSH) anti-obesity medications (AOM), which includes co- and tri-agonists that combine peptides such as GLP-1, glucose-dependent insulinotropic polypeptide (GIP), amylin, and glucagon, is poised to commence clinical trials in adolescents." (PMID 40014613, 2025). "To date, no large scale RCTs have evaluated GLP‐1RAs or the dual GIP/GLP‐1 RA tirzepatide in HFrEF (with or without obesity)." (PMID 41309245, 2025). "VK2735 is a new anti-obesity drug that mimics the action of both GLP-1 and GIP." (PMID 40282955, 2025). "The AASD recommends lifestyle changes in the form of a reduced-calorie diet and increased physical activity, together with new anti-obesity medications, including GLP-1 RA and dual GIP/GLP-1 receptor agonists, as first-line treatment for patients with obesity, prediabetes, and type 2 diabetes." (PMID 39881371, 2025). "A GLP-1 RA with GIP (glucose-dependent insulinotropic polypeptide), tirzepatide, has been approved for moderate-to-severe OSA with obesity due to its efficacy in reducing apnea severity, achieving sleep apnea resolution (AHI < 5 or AHI 5–14 without excessive daytime sleepiness) and weight reduction." (PMID 40807063, 2025). "Although the GIP and GIP receptor system is known to promote energy assimilation and contribute to obesity, the fact that a dual GIP/GLP-1R agonist exhibited stronger anti-obesity effects than GLP-1RAs alone was unexpected." (PMID 40607142, 2025). "The therapeutic landscape of obesity and T2D has been profoundly transformed by the emergence of incretin-based pharmacotherapies, particularly GLP-1 RAs and, more recently, dual and triple agonists targeting GLP-1, GIP, and GCG receptors." (PMID 41465555, 2025). "Pharmacotherapy plays a central role in obesity management, particularly with the emergence of incretin-based therapies such as glucagon-like peptide 1 (GLP-1) receptor agonists and dual glucose-dependent insulinotropic peptide (GIP)/GLP-1 receptor agonists." (PMID 41155711, 2025). "The latest obesity drug to be evaluated in clinical trials, retatrutide (a GLP-1, GIP and glucagon triple receptor agonist), has only recently undergone phase-two studies for type 2 diabetes and obesity, without a lifestyle intervention component in either study." (PMID 38459258, 2025). "Incretin-based anti-obesity therapies (e.g., GLP-1 receptor agonists such as semaglutide; dual GIP/GLP-1 agonists such as tirzepatide) improve adiposity, insulin resistance, and inflammatory profiles, providing a biologically plausible pathway for endometrial risk modification." (PMID 41301707, 2025).